IL6 (interleukin 6)
Diseases named in the same sentence as IL6 in open-access papers (continued):
Sharing a sentence is not in itself a finding about the gene and the disease.
benign tumors (23 papers, 2011 to 2025). "In particular, IL-6 contributes to maintaining pituitary senescence during tumorigenesis by its autocrine action, providing an IL-6-mediated benign tumour senescence model." (PMID 35837315, 2022). "In summary, to our knowledge, this is the first research targeted at the profile of IL-6 in both plasma and PF of patients with different clinical manifestations of OC in comparison to benign tumors and healthy donors." (PMID 33062717, 2020). "Our result is supported by a previous study which showed that IL-6 was as an independent predictor of an accumulated postoperative 3MH/Cr level in patients underwent open heart surgery." (PMID 32414332, 2020). "Proinflammatory markers including serum C-reactive protein, IL-6, and IL-8 have all been used in clinical studies in an attempt to differentiate between normal, benign tumor, and OC." (PMID 25403235, 2014). "In conclusion, we found that higher serum IL-6 level was associated with the presence of STS as opposed to benign tumors." (PMID 28851899, 2017). "One recent study reported that the IL-6 is strongly associated with advanced EOC and that the IL-6 findings could be useful in combination with serum levels of CA-125 to differentiate between benign tumors and EOC." (PMID 28848618, 2017). "Previous studies have indicated that LD has antiinflammation effect and that the inflammatory response participates in I/R-induced cardiac injury; thus the effects of LD on inflammatory cytokines (IL-6, TNF-α and CRP) were also detected in the ischemic heart." (PMID 26058040, 2015). "Thus, plasma mediators released in the circulation 4 h after open heart surgery strongly suppressed LPS-induced TNF-α but not IL-6 synthesis by monocytes." (PMID 22506067, 2012). "In the present study, human CF produced IL-6, IL-8, and IFN-β, but it is likely that their physiological amounts are not so high to induce heart inflammation." (PMID 33881711, 2021).
myopathy (23 papers, 2011 to 2025). A disease of the muscle in which the muscle fibers do not function properly. "The pro-inflammatory cytokines, particularly interleukin 6 (IL-6) released by the injured cells, damage the skeletal muscle and manifest as myopathy." (PMID 35862378, 2022). "We chose the cytokines bFGF, IFN-γ, EGF and IL-6 that are related to myopathy and or cirrhosis, and found that, bFGF is negatively correlated and the remaining three cytokines are positively correlated to MYO18B mRNA expression." (PMID 32704163, 2020). "Future studies could include the evaluation of inflammatory indices such as tumour necrosis factor α and interleukin 6 to further elucidate the role of inflammation in CF myopathy." (PMID 36478293, 2023). "Inhibition of TLR4 and HMGB1 signaling significantly reduced the expression of TNF-α and IL-6 cytokines in a myopathy mouse model, suggesting that the HMGB1/TLR4 axis may involve in skeletal muscle atrophy." (PMID 36497194, 2022). "Furthermore, upregulation of Nogo-A in dystrophin-deficient (mdx) murine model, myopathy and Duchenne muscle dystrophy (DMD) clinical biopsies was associated with upregulation of CHOP, IL-6 and TNF-α." (PMID 33572505, 2021). "Lower levels of two anabolic growth mediators, (IGF and GH), and a higher level of the catabolic cytokine IL-6 were observed in this study and point to an imbalance which could contribute to some of the myopathies and growth delays present in BTHS patients." (PMID 22721508, 2012). "Resistin expression in muscle tissue was significantly higher in patients with inflammatory myopathies compared to controls, and resistin induced the expression of interleukins (IL)-1β and IL-6 and monocyte chemoattractant protein (MCP)-1 in mononuclear cells but not in myocytes." (PMID 22577940, 2012). "Muscle biopsies from myopathy and DMD patients had significant increases in Nogo-A, CHOP, IL-6, and TNF-α expression at both the mRNA and protein levels." (PMID 33572505, 2021). "Idiopathic inflammatory myopathies stem from imbalances in cytokine signaling and T-cell dysregulation, creating a proinflammatory environment which fuels the disease process, including IFNs, TNF-alpha, janus kinases, IL-6, etc." (PMID 40297385, 2025). "Finally, we found that myopathy and DMD patients group (n=10) had significantly elevated levels of Nogo-A, CHOP, IL-6, and TNF-α mRNA compared with healthy subjects group (n=5)." (PMID 33572505, 2021). "We hypothesized IL-6 and TNF-α may be involved in ET-1–induced inflammatory myopathy." (PMID 35468098, 2022).
brain diseases (22 papers, 2007 to 2025). "Inhibiting the activation of NF-κB signals in microglia and neurons observably mitigate neuroinflammation in brain disease, manifested by down-regulation of pro-inflammatory mediators, such as IL-6, IL-18, iNOS and COX-2, and the loss of neurons." (PMID 37600790, 2023). "Elevated levels of IL-6 have also been adversely associated with several brain diseases." (PMID 29879988, 2018). "Taken together, these data suggest that glycerophospholipid metabolism and tryptophan-kynurenine metabolite secretions are important (and potentially related) metabolic pathways by which IL-6 inflammation affects the developing nervous system and predisposes it to developing a brain disease." (PMID 25374324, 2014). "IL-8 is a major chemotactic factor for a variety of leukocytes and increased IL-6 in the central nervous system has been associated with brain disease in SIV-infected macaques and has been implicated as a critical controlling element in brain disease in the SIV-macaque model." (PMID 17498309, 2007). "The pleiotropic effects of IL-6 impede the development of strategies that can target the IL-6 response in brain diseases." (PMID 40843259, 2025). "Following activation, Mincle and its downstream syk increase inflammatory cytokine production, such as TNF-α and IL-6, by regulating the NFκB signal in brain diseases." (PMID 37189208, 2023). "IDO1 plays a critical pathogenic role in brain disorders when activated by proinflammatory cytokines, such as interferon γ (IFN-γ), interleukin-6 (IL-6), and tumor necrosis factor α (TNF-α)." (PMID 37191427, 2023). "Of note, IL-6 is a major cytokine in the central nervous system, that has been related to many brain diseases, among which MS." (PMID 24236019, 2013). "The level of IL-6 obviously contributes to the pathogenesis of brain diseases." (PMID 40843259, 2025). "However, no studies in the literature have discussed how exercise affects this highly conserved membrane-proximal region of the receptors, thereby interrupting the IL-6-mediated JAK/STAT signaling in brain diseases." (PMID 40843259, 2025). "IL-6 is recognized as a crucial inflammatory mediator in brain diseases." (PMID 35453404, 2022). "The method of down-regulation of IL-1β by RNA interference during HI may protect against drain edema, stoke and other brain disorders via up-regulation of IL-6 expression." (PMID 24965599, 2015). "Therefore, understanding their involvement in activating or deactivating IL-6 expression could provide a potential therapeutic target for treating brain diseases." (PMID 40843259, 2025). "In addition, studies have shown that moderate physical exercise could reduce the levels of IL-1β and TNF-α in the hippocampus or serum in interventions for brain disorders, although the effect on IL-6 is subject to specific discussion." (PMID 36212646, 2022). "Therefore, PPAR-γ expression stimulants not only accelerate the inhibition of NF-κB DNA-binding activity, but also suppress the acute phase of neuroinflammation mediated by IL-6; this suggests that it could be a promising therapeutic strategy in most brain disorders." (PMID 35684465, 2022). "While normal physiological levels of IL-6 and TNF-α protect neurons and glia against glutamate-induced toxicity, elevated levels and toxicity can arise under conditions of hypoxia and brain damage, and are seen in a number of brain disorders." (PMID 20509936, 2010). "However, the mechanism of how peripheral IL-6 mediated the brain disorder was not studied in these studies." (PMID 36160165, 2022). "The release of inflammatory cytokines such as interleukin (IL)-1, IL-6, IL-17 and tumor necrosis factor alpha (TNF-α) which have been incriminated as being part of pathological signal cascades in brain diseases could have been released in these animals, although these cytokines were not measured." (PMID 28686693, 2017).
brain diseases (continued). "Our discovery that IL-6 expression is central to C3 induction by HIV in astrocytes may provide an avenue to new therapeutic investigations in this common pathway to diverse brain diseases plaguing mankind." (PMID 28122624, 2017).
neurodevelopmental disorder (19 papers, 2014 to 2026). A behavioral and cognitive disorder with onset during the developmental period that involves impaired or aberrant development of intellectual, motor, or social functions. "IL-6 and IL-8, in particular, play dual roles: they are crucial for pathogen defense but are also associated with preterm labor and neurodevelopmental disorders." (PMID 41450943, 2025). "Elevated maternal interleukin 6 (IL-6) during pregnancy has been associated with adverse fetal brain development and neurodevelopmental disorders, which often involve executive functioning (EF) impairments." (PMID 40211088, 2025). "Further studies have shown that elevated maternal serum IL-6 levels are associated with altered amygdala and brain connectivity in the offspring, which is common in children with neurodevelopmental disorders (NDDs)." (PMID 36293994, 2022). "Prematurity is a recognised population risk factor for neurodevelopmental disorders and our findings agree with the literature associating preterm-birth with depressed/stress pregnancies, and higher IL-6 concentrations." (PMID 35784438, 2022). "At present, many inflammatory cytokines have been reported to be significantly associated with CP or neurodevelopmental disorders, such as IL-6, IL-8, IL-10, and IL-17." (PMID 33324152, 2020). "As a consequence, an increase in pro-inflammatory cytokines (e.g., IL-1B, IL-6, IL-8, and IL-12p40) was observed, which are associated with impaired social communication and neurodevelopmental disorders." (PMID 31752095, 2019). "Maternal immune activation (MIA) increases the risks for neurodevelopmental disorders in offspring through inflammatory cytokines, including interleukin-6 (IL-6)." (PMID 37921007, 2023). "Several inflammatory cytokines have been identified as being involved in CP or other neurodevelopmental disorders, such as IL-6, IL-8, and IL-17." (PMID 33324152, 2020). "Notably, two key proinflammatory cytokines, IL-6 and IL-17, are capable of crossing the placental barrier and binding to receptors on fetal brain cells, potentially initiating neurodevelopmental disorders." (PMID 40276707, 2025). "Together, type I IFN-signaling cascades to induce IFITM3 and IL-6 may be possible targets for neurodevelopmental disorders triggered by perinatal immune activation." (PMID 26633355, 2015). "Elevated levels of inflammatory cytokines such as IL-6, IL-1β, and TNF-α in blood and cerebrospinal fluid have been reported in patients with neurodevelopmental disorders." (PMID 41465426, 2025). "The selected cytokines comprised IL-1β, IL-6, IL-10, TNF-α, and IFN-γ, which have not only been found dysregulated in the MIA paradigm, but also form part of the inflammatory profiles in the neurodevelopmental disorders reflected in the MIA model (eg)." (PMID 39033141, 2024). "The response of each cell type presented here lies within the context of an acute IL-6 treatment in a monoculture, in the absence of a genetic background for a relevant psychiatric or neurodevelopmental disorder." (PMID 36781081, 2023). "In this way, the dysregulation of IL-1β and IL-6 (altered in ASD and ADHD adolescents in this study) could represent potential biomarkers of both neurodevelopmental disorders, ASD and ADHD." (PMID 37511467, 2023). "Thus, the possibility for inhibiting the cross-talk between IL-6 and IFN-γ in preventing neurodevelopmental disorders that are potentially inflammation-dependent such as ASD presents an attractive therapeutic approach." (PMID 36300375, 2022). "Although this cytokine is crucial for normal embryo implantation, IL-6 appears to be the main circulating mediator of the inflammatory response in MIA models, and its upregulation leads to early damage of dopaminergic neurons and neurodevelopmental disorders in the offspring." (PMID 35963926, 2022).
connective tissue disease (17 papers, 2010 to 2025). "Simpson and Hirsch have validated the association between IL-6 and connective tissue diseases associated with PAH." (PMID 37449201, 2023). "The inclusion of different categories of type I PAH (notably connective tissue disease associated PAH) also increases the median levels for IL-6." (PMID 35063447, 2022). "It appears that IL-6 blockade may hold promise as an adjunct drug in treatment of PAH in idiopathic form as well as in association with connective tissue disease." (PMID 20981316, 2010). "Simpson et al15 reported median levels of 2.24 pg/mL (interquartile range, 1.09 to 4.33 pg/mL) in connective tissue disease associated PAH and 1.62 pg/mL (interquartile range, 0.72 to 2.94 pg/mL) in idiopathic PAH, which implies that IL-6 levels are disease- and genotype-specific." (PMID 35063447, 2022). "This supports that protective effects of IL6 signaling inhibition may be specific to AAA arising secondary to atherosclerotic risk factors rather than due to pre-existing rheumatological disease or connective tissue disease." (PMID 39633572, 2025). "Studying the impact of pro-inflammatory cytokines like tumor necrosis factor-alpha (TNF-α) and interleukin-6 (IL-6) on placental dysfunction and FGR in patients with connective tissue disorders could lead to targeted interventions." (PMID 38993471, 2024). "Targeting IL-6 in several diseases (including PsA, axSpA or connective tissue diseases, except for ILD in SSc) was not effective in several clinical trials." (PMID 36260501, 2022).
head and neck tumor (16 papers, 2014 to 2025). "Through GSEA analysis, we revealed the mechanism by which CTSL acts through the IL6‐JAK‐STAT3 pathway in head and neck tumours." (PMID 39893643, 2025). "It has been confirmed that IL-6 is involved in the epithelial to mesenchymal transition in head and neck tumor cells via the activation of the STAT3/SNAIL signaling pathway, and STAT3 knock down significantly reverses IL-6-mediated EMT changes." (PMID 34943943, 2021). "On the other hand, it has been shown that IL-6 promotes head and neck tumor metastasis by inducing EMT." (PMID 32570756, 2020). "This was observed even in presence of the IL-6 secreted by the head and neck tumor cells, which we know is at lower constitutive levels than the IL-6 expressed by the endothelial cells." (PMID 29245982, 2017). "The STAT3 signaling also mediates IL-6 induced EMT (epithelial-mesenchymal transition) to promote the metastasis of head and neck tumor cells." (PMID 27012679, 2016). "Recently, IL-6 was shown to promote head and neck tumor metastasis by inducing EMT via the JAK-STAT3-SNAIL signaling pathway." (PMID 26267319, 2015). "According to a study, IL-6 promotes EMT in head and neck tumors by altering Snail expression." (PMID 38519574, 2024). "IL6 was confirmed to promote head and neck tumor metastasis." (PMID 25970784, 2015).
gastrointestinal disease (15 papers, 2015 to 2025). A disease that occurs in the gastrointestinal system, excluding the hepatobiliary system. "Recent studies have shown that many gastrointestinal diseases can lead to poor sleep, and cytokines, such as interleukin-1 and interleukin-6, have been shown to be associated with sleep dysfunction." (PMID 36837398, 2023). "Implementing a proactive monitoring program for assessing the risk of gastrointestinal diseases in UC patients, particularly those with elevated IL-6 levels, may be of interest." (PMID 38529201, 2024). "IL-6 maintains homeostasis by stimulating the proliferation and triggering an increase in neutrophil count, and IL-10 has been found to be negatively correlated with the occurrence and progression of gastrointestinal disease." (PMID 37819128, 2023). "Cytokine-mediated dysfunction of tight junctions is important in gastrointestinal disease as cytokines and other growth factors may act to alternatively decrease (e.g., IL-10) or increase (e.g., IL-6) gut permeability." (PMID 30669283, 2019). "We know that alterations of cytokines like interleukin-1 (IL-1), IL-6, and tumor necrosis factor-alpha (TNF-alpha) are known manifestations in various gastrointestinal diseases, including CRC." (PMID 34523041, 2022). "Recent studies using rat models of gastrointestinal disease have found that taVNS upregulates intestinal ACh and α7nAChR expression, while simultaneously reducing the levels of inflammatory cytokines such as TNF-α, IL-1β, and IL-6." (PMID 40564012, 2025).
gastrointestinal disorders (14 papers, 2015 to 2025). "Immunomodulation:- ↓ IL6 and ↑ IL-10.Management of gastrointestinal disorders:- Most efficient treatment efficacy by producing the quickest therapeutic effect.- No recurrence of IBD at least for 6 months after the experiment." (PMID 37954670, 2023). "Pro-inflammatory cytokines such as IFN-γ, TNF-α, IL-1, and IL-6 are measured as biomarkers for gastrointestinal disorders, including ETEC-infection diarrhea." (PMID 35747266, 2022). "Il-6 is cytokine that drives inflammation and is an accepted marker of inflammatory changes, especially in gastrointestinal disorders." (PMID 26448758, 2015). "However, we also found an inverse correlation between pro-inflammatory IL-6 and symptoms of gastroenteropathy." (PMID 37189645, 2023). "Clinical reports of IL-6 responses in humans with gastrointestinal disorders have found significantly higher blood IL-6 concentrations in ischemic versus non-ischemic intestinal disease, and IL-6 was found to be both sensitive and specific in a small population of patients with ischemic bowel." (PMID 36670767, 2023). "Moreover, we verified whether the expression levels of hsa‐let7‐5p was correlated with any inflammatory markers, such as IL‐6, TNF‐α, fibrinogen, and D‐dimer and with specific diseases symptoms, such as fever, dry cough, dyspnea, and gastrointestinal disorders." (PMID 36073344, 2022).
musculoskeletal disorders (12 papers, 2011 to 2025). "IL-6 is a key pro-inflammatory cytokine involved in both acute and chronic inflammatory responses, and its reduction has been associated with improved clinical outcomes in musculoskeletal disorders." (PMID 40648913, 2025). "However, a systemic inflammatory component secondary to the release of inflammatory mediators produced by adipocytes, namely adipokines and inflammatory cytokines such as interleukin (IL)-6, has also been implicated in the pathogenesis of musculoskeletal disease." (PMID 34419023, 2021). "Interleukin-6 (IL-6) signaling contributes significantly to inflammation in musculoskeletal diseases and musculoskeletal pain states." (PMID 39000275, 2024). "For example, serum levels of TNF-α, IL-1β and IL-6 correlate positively with presence of musculoskeletal disorders symptoms in patients, and TNF-α levels are even predictive of symptom severity." (PMID 24015193, 2013). "This is of interest because tissues collected from humans with upper extremity work-related musculoskeletal disorders show the presence of fibrosis and its mediators, including IL-6 and TGFB1." (PMID 24015193, 2013). "Specifically, EA can modulate the release of pro-inflammatory cytokines such as IL-6, TNF-α, and IL-1β, which are key mediators of the inflammatory response in musculoskeletal disorders." (PMID 41567770, 2025). "Serum TNF-α, IL-6, TGFB1, CTGF and MMP2 may serve as serum biomarkers of work-related musculoskeletal disorders, although further studies in humans are needed." (PMID 24015193, 2013).